RNU6-68P (RNA, U6 small nuclear 68, pseudogene)
Synonyms: RNU6-68
Gene: Small nuclear RNA gene on chromosome 13 (46,410,454 to 46,410,557, forward strand). Ensembl gene ENSG00000252385.
Homologues: Orthologues: chimpanzee U6 (97% identical), macaque U6 (88% identical), pig U6 (74% identical). Paralogues in human: RNU6-81P (98% identical), RNU6-886P (84% identical), RNU6-1152P (83% identical), RNU6-15P (83% identical), RNU6-166P (83% identical), RNU6-266P (83% identical), RNU6-536P (83% identical), RNU6-589P (83% identical), RNU6-672P (83% identical), RNU6-869P (83% identical), RNU6-1060P (82% identical), RNU6-1131P (82% identical), and 1288 more.